CDIPT (CDP-diacylglycerol--inositol 3-phosphatidyltransferase)
Description:
Catalyzes the biosynthesis of phosphatidylinositol (PtdIns) as well as PtdIns:inositol exchange reaction. May thus act to reduce an excessive cellular PtdIns content. The exchange activity is due to the reverse reaction of PtdIns synthase and is dependent on CMP, which is tightly bound to the enzyme.
Synonyms: PIS; PIS1
Tractability: Antibody: UniProt places it where antibodies can reach, with high confidence; UniProt predicts a signal peptide or a membrane-spanning region; its Gene Ontology location is reachable by antibodies, with medium confidence; the Human Protein Atlas places it where antibodies can reach. PROTAC: ubiquitination databases record sites on it; its protein half-life has been measured.
Target class: Enzyme; Transferase
Gene: Protein-coding gene on chromosome 16 (29,858,357 to 29,863,414, reverse strand). Ensembl gene ENSG00000103502.
Subcellular location: Endoplasmic reticulum membrane; Cell membrane
Subcellular location (Human Protein Atlas): Nuclear membrane; Nucleoplasm; Plasma membrane
Pathways (Reactome):
Metabolism: Synthesis of PI
Gene Ontology:
Molecular function: CDP-diacylglycerol-inositol 3-phosphatidyltransferase activity; protein binding; alcohol binding; carbohydrate binding; diacylglycerol binding; manganese ion binding; phosphotransferase activity, for other substituted phosphate groups
Biological process: phosphatidylinositol biosynthetic process; CDP-diacylglycerol metabolic process; phospholipid biosynthetic process
Cellular component: membrane; endoplasmic reticulum membrane; plasma membrane
Genetic constraint (gnomAD): Loss-of-function variants: 11 observed, 17.48 expected, observed/expected ratio (o/e) 0.63, 90% interval 0.4 to 1.04. The upper end of that interval is the gene's LOEUF score, 1.04, which puts it in group 4 of 6, group 1 being the genes least tolerant of losing a copy. Missense variants: 230 observed, 250.13 expected, observed/expected ratio (o/e) 0.92, 90% interval 0.82 to 1.03. Synonymous variants: 104 observed, 102.95 expected, observed/expected ratio (o/e) 1.01, 90% interval 0.86 to 1.19.
Homologues: Orthologues: chimpanzee CDIPT (100% identical), macaque CDIPT (99% identical), mouse Cdipt (96% identical), pig CDIPT (96% identical), guinea pig CDIPT (95% identical), rat Cdipt (95% identical), tropical clawed frog cdipt (76% identical), dog CDIPT (69% identical), zebrafish cdipt (69% identical), Drosophila melanogaster Pis (50% identical), Caenorhabditis elegans pisy-1 (48% identical).
Diseases named in the same sentence as CDIPT in open-access papers:
CDIPT is named in the same sentence as 23 diseases in open-access papers, as found by Europe PMC text mining. Sharing a sentence is not in itself a finding about the gene and the disease. The quoted sentences say what the papers report.
oral cancer (4 papers, 2010 to 2023). "Previous studies linked abnormal CDIPT function to diseases like oral cancer or hepatic steatosis in zebrafish." (PMID 37040172, 2023).
gastric cancer (2 papers, 2013 to 2023). A primary or metastatic malignant neoplasm involving the stomach. "In gastric cancer, CDIPT plays a crucial role in tumorigenesis and progression." (PMID 37004045, 2023).
Hepatic steatosis (2 papers, 2023). Steatosis is a term used to denote lipid accumulation within hepatocytes. "Also in zebrafish, deficiency in CDP-diacylglycerol-inositol 3-phosphatidyltransferase (Cdipt) impairs phosphatidylinositol synthesis, leading to ER stress and hepatic steatosis by an unknown mechanism." (PMID 37373143, 2023).
Obesity (2 papers, 2012 to 2023). Accumulation of substantial excess body fat. "Copy number variations (CNVs) in CDIPT have also been described in individuals with obesity or neurological disorders." (PMID 37040172, 2023). "Out of the 5 genes identified as optimal predictors, 3 (ie, CDIPT, MRC2, and SUMO3) have been previously shown to be associated with T2D or obesity." (PMID 37040172, 2023).
colorectal cancer (1 paper, 2025). A primary or metastatic malignant neoplasm that affects the colon or rectum. "For CDIPT, there are essentially no published data on colorectal cancer; its positive correlation with RBP4 in our set, therefore, represents a novel observation that may reflect shared lipid/inositol metabolism but remains to be experimentally validated." (PMID 41007818, 2025).
cancer (7 papers, 2010 to 2025). A tumor composed of atypical neoplastic, often pleomorphic cells that invade other tissues. "In addition, CDS2 and CDIPT are significantly co-dependent in DepMap cancer cell lines, which is indicative of a similar mechanism of dependency 28,57." (PMID 40615674, 2025). "Most of these genes, such as CDIPT, PIK3C2G, ARSJ, ARSE, GLA and GLB2, had not been studied in cancers." (PMID 31475440, 2019).
CDIPT also shares sentences with these, for which no sentence is quoted: oral squamous cell carcinoma (3 papers); tumor (3); retinal degeneration (2); alpha 1-antitrypsin deficiency (1); asthma (1); bacterial infections (1); breast carcinoma (1); chronic obstructive pulmonary disease (1); hepatocellular carcinoma (1); leukoplakia (1); liver disease (1); lung disease (1); neurological disorders (1); Palmoplantar hyperkeratosis (1); Pythiosis (1); tongue cancer (1); Zinc deficiency (1).